AFP (alpha fetoprotein)
Diseases named in the same sentence as AFP in open-access papers (continued):
Sharing a sentence is not in itself a finding about the gene and the disease.
benign teratomas (6 papers, 2012 to 2025). "AFP is an important marker for the clinical differentiation between benign teratomas (within the normal range) and malignant teratomas (higher than the normal range)." (PMID 37781207, 2023). "Serum AFP levels were persistently high in a patient with recurrence of benign teratomas in multiple locations." (PMID 37781207, 2023). "AFP detection is helpful in the differential diagnosis of malignant and benign teratomas before surgery and is an important indicator for monitoring metastasis and recurrence after surgery." (PMID 36795187, 2023). "Markers such as AFP and beta-hCG are typically within reference range in benign teratomas but can be produced in high levels by malignant embryonal tumors." (PMID 31118058, 2019). "Laboratory exams are often normal, and serum levels of human chorionic gonadotropin and alpha-fetoprotein are always normal in patients with benign teratoma." (PMID 27144046, 2016).
cholestasis (6 papers, 2016 to 2025). Impairment of the bile flow caused by obstruction within the liver, or outside the liver in the bile duct system. "Elevated AFP levels were recorded during the first 3 months of life, correlated with the presence of cholestasis and decreased when cholestasis resolved." (PMID 35455589, 2022). "AFP levels peaked during the initial test and gradually declined as cholestasis resolved in most patients." (PMID 35455589, 2022). "In most patients, AFP levels peaked during the initial test and declined over time as cholestasis resolved." (PMID 35455589, 2022).
co-infection (6 papers, 2015 to 2025). "We compared HCV RNA and liver enzyme (ALT, AST, albumin, bilirubin, GGT, AFP) levels in acute, HCV mono-infection, and HIV-HCV coinfection." (PMID 30865664, 2019).
cystic teratoma (6 papers, 2010 to 2026). "Although the prognosis for FIF is more favorable than for cystic teratoma, the presence of immature elements nevertheless indicates the need for close clinical, radiological and serological (AFP) follow-up." (PMID 20338036, 2010). "Normal AFP and histopathology confirmed mature cystic teratoma without immature or malignant elements." (PMID 41523223, 2026). "We reported a case of a primary mature cystic teratoma in the right adrenal gland in an adult with no any signs or symptoms and with unremarkable outcome of laboratory testing for adrenal hormone, AFP and hCG." (PMID 26582506, 2015). "Additionally, AFP is not usually elevated in mixed GCTs, more so in cases involving mature cystic teratoma, even with YST as a component of the tumour, as seen in the index patient who had a normal AFB value of 5 ng/mL (normal: 0-10 ng/mL)." (PMID 42317923, 2026).
depression (6 papers, 2021 to 2025). "This study sought to investigate the potential contributory role of sleep disturbances and depression in cancer risk by analyzing levels of CA125, CA199, AFP, and CEA." (PMID 39473919, 2024).
Hepatic hemangioma (6 papers, 2015 to 2025). A congenital vascular malformation in the liver composed of masses of blood vessels that are atypical or irregular in arrangement and size. "The abdominal ultrasound examination and CT scan performed on the present patient revealed a localized hepatic nodule with the characteristics of hepatic hemangioma, while the highly elevated AFP and CEA levels suggested HCC." (PMID 25624892, 2015). "Combined with imaging examination and AFP (−), it was considered as a hepatic hemangioma." (PMID 35967548, 2022).
malignant teratoma (6 papers, 2010 to 2024). A malignant form of teratoma. "Despite the AFP levels before and after surgery remaining at normal values, a possible recurrence of a malignant teratoma after FIF resection must best be kept in mind." (PMID 20338036, 2010). "Alpha-fetoprotein (AFP) level was elevated in both malignant teratomas and ESTs." (PMID 26504900, 2015). "The serum levels of alpha-fetoprotein (AFP), beta human chorionic gonadotrophin (BHCG) and carbohydrate antigen 19-9 (CA 19-9) can be raised in malignant teratomas." (PMID 33438088, 2021).
malnutrition (6 papers, 2021 to 2025). Inadequate nutrition resulting from poor diet, malabsorption, or abnormal nutrient distribution. "Univariate Cox regression analysis revealed several factors significantly associated with poor OS (all p < 0.05): AFP ≥ 400 ng/mL; malnutrition (both moderate and severe); serum albumin <35 g/L; maximum tumor diameter >5 cm; tumor number ≥3; and presence of MVI." (PMID 40642170, 2025). "The following independent risk factors for post-hepatectomy OS in patients with HCC were identified: AFP ≥ 400 ng/mL; Malnutrition; serum albumin <35 g/L; maximum tumor diameter >5 cm; tumor and number ≥3." (PMID 40642170, 2025). "Multivariate Cox regression analysis identified the following independent risk factors for OS in patients with HCC undergoing hepatectomy: AFP ≥ 400 ng/mL; Malnutrition; serum albumin <35 g/L; maximum tumor diameter >5 cm; and tumor number ≥3." (PMID 40642170, 2025). "Malnutrition, growth retardation, severely decreased VA levels, and significantly increased AFP levels could provide reference for the diagnosis and differential diagnosis of NICCD." (PMID 39872914, 2024). "Based on the results of multivariate Cox regression analysis, the following predictors were identified for post-hepatectomy OS in patients with HCC: serum albumin, alpha-fetoprotein (AFP), maximum tumor diameter, tumor number, and GLIM malnutrition grade." (PMID 40642170, 2025).
metastatic carcinoma (6 papers, 2015 to 2025). A carcinoma which has spread from the original site of growth to another anatomic site. "Differential diagnoses of AFP+ EC include endometrioid, clear cell, serous, and gastric-type uterine carcinoma, and metastatic carcinoma." (PMID 34977100, 2021). "We also emphasize the importance of adding HepPar-1 and AFP to the panel of immunohistochemical markers applied for identification of the primary site of metastatic carcinoma." (PMID 26122043, 2015). "The study found that serum Metrnβ levels were significantly higher in patients with AFP-negative HCC compared to those with AFP-positive HCC and metastatic carcinoma." (PMID 40429631, 2025). "In view of raised AFP, computed tomography scan features consistent with HCC, absence of other malignant lesions, and histopathology of the rib lesion consistent with metastatic carcinoma, a diagnosis of bony rib metastasis with HCC was made in our patient." (PMID 37554869, 2023). "The serum expression of IL-41 was highest in AFP negative HCC patients and significantly higher than that in AFP positive HCC and metastatic cancer patients." (PMID 38835390, 2024).
mixed germ cell tumor (6 papers, 2011 to 2025). A malignant germ cell tumor characterized by the presence of at least two different germ cell components. "ITs are typically not linked to increased levels of alpha-fetoprotein (AFP) or β-hCG unless they occur as part of a mixed germ cell tumor, as observed in our case." (PMID 40370888, 2025). "Three patients with mixed germ cell tumor who had elements of EST also had elevated AFP levels." (PMID 21988930, 2011). "Our research shows that a high level of AFP is related to the YST and mixed germ cell tumors, high tumor staging, and an AFP level ˃ 10,000 ng/mL is an independent adverse prognostic factor." (PMID 38001671, 2023). "Complete excision for pathological assessment was essential to rule out mixed germ cell tumors and inform the subsequent treatment plan, leading to a decrease in AFP levels and symptom alleviation." (PMID 39706145, 2025).
neuroendocrine carcinoma (6 papers, 2011 to 2025). A malignant neuroendocrine neoplasm composed of cells containing secretory granules that stain positive for NSE and chromogranin. "The majority of the tumor was a high-grade neuroendocrine carcinoma with features of a small cell carcinoma that was positive for chromogranin, synaptophysin, and cytokeratin 19 and negative for hepatocellular antigen and alpha-fetoprotein (AFP)." (PMID 29147223, 2011).
neuroendocrine tumors (6 papers, 2017 to 2026). "Prior to this study, only one case of an AFP-producing neuroendocrine neoplasm originating from the liver has been reported in the literature." (PMID 39522069, 2025). "AFP-producing hepatic neoplasms warrant extra caution, and this case emphasizes the importance of considering primary hepatic neuroendocrine neoplasms in the differential diagnosis of liver tumors." (PMID 39522069, 2025). "The clinical course of patients with an AFP-positive neuroendocrine tumor remains to be elucidated due to the rare occurrence." (PMID 37721573, 2023). "The present clinical findings for an AFP-positive neuroendocrine tumor of the thymus case are considered useful for establishing an optimal treatment strategy in the future." (PMID 37721573, 2023). "Although AFP-positive neuroendocrine tumor of the thymus is relatively rarer than germ cell carcinoma, differential diagnosis with use of a histological examination should be considered because of the potentially poorer prognosis." (PMID 37721573, 2023). "Therefore, the patient was diagnosed with an AFP-producing neuroendocrine neoplasm." (PMID 39522069, 2025). "In addition, AFP may serve as a prognostic factor for neuroendocrine tumors." (PMID 39522069, 2025).
omphalocele (6 papers, 2015 to 2024). Omphalocele is an embryopathy classified in the group of abdominal celosomias and is characterized by a large hernia of the abdominal wall, centered on the umbilical cord, in which the protruding viscera are protected by a sac. "Elevated maternal serum and amniotic fluid AFP levels are common diagnostic indicators of potential fetal abnormalities, such as neural-tube and ventral wall (omphalocele, gastroschisis) defects." (PMID 39224747, 2024). "Finally, high serum levels of alpha-fetoprotein have been associated with omphalocele." (PMID 33810554, 2021). "There is an additional increase in the maternal serum AFP in gastroschisis as compared to omphalocele; therefore, measuring maternal serum AFP increases is a less sensitive test to diagnose omphalocele than gastroschisis." (PMID 38021990, 2023). "Ultrasound detection in the first trimester of pregnancy of the association of an omphalocele with scoliosis will raise the suspicion of LBWC, and will prompt additional investigations such as measurement of the maternal serum alpha fetoprotein level." (PMID 37189514, 2023). "In contrast, elevation of Alpha Fetoprotein (AFP) in maternal serum is more likely to be observed in pregnancies with gastroschisis as compared to omphalocele." (PMID 33672248, 2021). "The elevation of acetylcholinesterase and alpha-fetoprotein (AFP) in the amniotic fluid with the absence of myelomeningocele is related to both omphalocele and gastroschisis." (PMID 38021990, 2023). "Prenatal ultrasound diagnosis of an omphalocele without liver is certain after 12 weeks of gestational age, but extra-abdominal liver tissue could be observed transvaginally at 9–10 weeks of amenorrhea, while an elevated maternal serum alpha-fetoprotein level may also be detected." (PMID 37189514, 2023).
sarcoma (6 papers, 2015 to 2025). A usually aggressive malignant neoplasm of the soft tissue or bone. "Besides, no specific serologic marker (such as CEA, AFP, and CA 19-9) is specific to sarcoma." (PMID 25880743, 2015).
autoimmune disease (5 papers, 2017 to 2025). A disorder resulting from loss of function or tissue destruction of an organ or multiple organs, arising from humoral or cellular immune responses of the individual to their own tissue constituents. "Recombinant expression of human AFP is under development as a biopharmaceutical for the treatment of autoimmune diseases, and human AFP is also being used as a bioactivated molecule in drug discovery studies for cancer treatment." (PMID 27913752, 2017). "AFP also plays an immunomodulatory role in the treatment of several autoimmune diseases, such as rheumatoid arthritis, multiple sclerosis, myasthenia gravis and thyroiditis." (PMID 27913752, 2017). "AFP is also an immunomodulatory molecule, as transfer of foetal AFP through the placenta into the mother’s circulation is correlated with remission of rheumatoid arthritis, multiple sclerosis and other autoimmune disorders." (PMID 27913752, 2017). "Malignancy, autoimmune disease, and inherited or acquired thrombophilias were all ruled out based on normal tumor markers (CA 19–9, CEA, AFP), ANA, antiphospholipid antibody panel, and imaging findings." (PMID 40692659, 2025).
clear cell carcinoma (5 papers, 2015 to 2025). "Since AFP+ EC can grow in solid, papillary, and glandular patterns with variable amounts of optically clear cells and hobnail-like cells and is positive for HNF1β on IHC at least weakly, clear cell carcinoma also looms as a serious diagnostic consideration." (PMID 34977100, 2021). "SALL4 is a highly sensitive and specific marker for OGCT and is particularly useful in differentiating yolk sac tumors from clear cell carcinoma, where other markers, such as AFP or glypican-3, show lower sensitivity and specificity." (PMID 41373846, 2025). "In this context, immunostaining with napsin A would be helpful, as it would be positive in clear cell carcinoma and negative in AFP+ EC." (PMID 34977100, 2021). "Another differential diagnosis of HCO includes endometrial carcinoma, clear-cell carcinoma and lipid cell tumor which are all AFP negative." (PMID 26213594, 2015).
cyst (5 papers, 2013 to 2024). A sac-like closed membranous structure that may be empty or contain fluid or amorphous material. "Cysts in neonates and infants can be observed if (i) the cyst is clearly from the ovary, (ii) the tumor markers AFP and ß-HCG are in age-related normal values or the AFP level shows a normal decrease, (iii) the cyst is not complex, and (iv) the patient is asymptomatic." (PMID 35937851, 2022). "Although it can appear as a large cyst with intracapsular septa and protrusion, the serum AFP of patients with cystadenoma of the ovary was negative." (PMID 38966065, 2024). "Brain imaging detected a bilobed cyst of the pineal gland, while serum and cerebrospinal baseline assessment initially ruled out raised alpha-fetoprotein or β-hCG levels." (PMID 36081625, 2022). "Some of these epithelial cysts expressed CK7 but not expressed hepatocytic marker AFP, suggesting that these cells could form cholangiocyte-like cyst structures with an epithelial polarity." (PMID 23935837, 2013).
endometrioid adenocarcinoma (5 papers, 2018 to 2025). An adenocarcinoma characterized by the presence of malignant glandular epithelial cells resembling endometrial cells. "Some reports in the previous literature have emphasized the similarity between AFP+ EC and secretory variant of endometrioid carcinoma, both being composed of tall columnar cells with clear cytoplasms." (PMID 34977100, 2021). "A few reports have characterized their cases of AFP-producing adenocarcinoma as endometrioid carcinoma, though relevant immunohistochemistry (IHC) is rarely reported." (PMID 34977100, 2021). "Histologically, the tumor was an endometrioid adenocarcinoma with sarcomatous element and a hepatoid component, the latter was immunohistochemically positive for alpha-fetoprotein, HepPar-1, and arginase-1." (PMID 29992073, 2018). "However, GCTs abundantly express germ cell markers, serum AFP in particular: this is the major difference between GCTs and endometrioid carcinoma." (PMID 32064359, 2020). "A diagnosis of high-grade endometrioid adenocarcinoma with YST differentiation was rendered based on the morphologic features and immunopositivity for SALL-4, glypican-3, and AFP." (PMID 41510478, 2025).
Hydrocephalus (5 papers, 2006 to 2025). Hydrocephalus is an active distension of the ventricular system of the brain resulting from inadequate passage of CSF from its point of production within the cerebral ventricles to its point of absorption into the systemic circulation. "We wished to determine the distribution of maternal serum alpha-fetoprotein levels associated with fetal hydrocephalus in a population-based screening program in Manitoba, and their potential relationship to additional anomalies." (PMID 16824231, 2006). "May present with elevated maternal alpha-fetoprotein levels, ventriculomegaly, hydrocephaly, cardiac and ocular defects.Also, only a renal form with nephrotic proteinuria has been described until adolescence." (PMID 40115110, 2025). "Since Seppala and Unnerus first suggested a possible association between elevated AFP levels and fetal hydrocephalus, there has been a relative lack of information about the subject in the literature." (PMID 16824231, 2006). "Although maternal serum alpha-fetoprotein (MSAFP) is a highly sensitive marker for certain congenital malformations such as open neural tube and ventral wall defects, its usefulness as a screening test for fetal hydrocephalus is uncertain." (PMID 16824231, 2006).
Hyperglycemia (5 papers, 2011 to 2024). An increased concentration of glucose in the blood. "The VFMAP scoring system, based on VTQ, fasting hyperglycemia, sex, age, and AFP level, could accurately predict the development of HCC in HCV patients who achieved SVR after DAA therapy." (PMID 38147196, 2024). "In addition to tumor size, other prognosis biomarkers have been found for liver malignancies after RFA, such as lymphocyte-to-monocyte ratio, AFP, and hyperglycemia." (PMID 36883222, 2023). "Indeed, we have identified a chimeric FGF19v protein that fits these criteria; it ameliorates hyperglycemia and hyperinsulinemia without a detectable increase in hepatic AFP expression in ob/ob mice." (PMID 21437243, 2011).
Jaundice (5 papers, 2019 to 2025). Yellow pigmentation of the skin due to bilirubin, which in turn is the result of increased bilirubin concentration in the bloodstream. "Breastmilk jaundice may occur due to certain factors present in human breastmilk (i.e., IL 1ß, IL6, ß-glucuronidase, epidermal growth factor, alpha-fetoprotein), which inhibits the conjugation of bilirubin that facilitates its excretion." (PMID 31440488, 2019).
measles (5 papers, 2018 to 2024). A highly contagious viral infection caused by the measles virus. "For immunization program performance, prioritized indicators included the numbers of measles and rubella, AFP, and neonatal tetanus cases reported in the aggregate IDSR system compared to the individual-level, case-based surveillance reporting system." (PMID 38932375, 2024). "The respondents indicated that their IDSR/EWARN systems were linked with other systems (e.g. alpha-fetoprotein (AFP), measles, malaria)." (PMID 36158929, 2022).
nonalcoholic steatohepatitis (5 papers, 2020 to 2023). "In patients with nonalcoholic steatohepatitis, the GALAD score, which determines the risk of HCC based on a patient’s sex, age, and serum levels of AFP, AFP-L3, and PIVKA-II, identified patients with any-stage HCC with an area under the curve (AUC) of 0.96." (PMID 35271670, 2022).
oesophageal varices (5 papers, 2013 to 2025). "Independent predictors of poorer survival included the presence of cardiac disease or oesophageal varices, a Child-Pugh score of 6, tumour size, and elevated alpha-fetoprotein (AFP) levels." (PMID 40647548, 2025).